RN7SKP242 (RN7SK pseudogene 242)
Gene: Miscellaneous RNA gene on chromosome 9 (83,200,940 to 83,201,228, reverse strand). Ensembl gene ENSG00000251776.
Homologues: Orthologues: chimpanzee 7SK (93% identical), mouse Gm55389 (40% identical), mouse Gm54881 (39% identical). Paralogues in human: RN7SKP180 (58% identical), RN7SKP9 (56% identical), RN7SKP225 (56% identical), RN7SKP255 (56% identical), RN7SKP38 (56% identical), RN7SKP174 (55% identical), RN7SKP192 (55% identical), RN7SKP237 (55% identical), RN7SKP250 (55% identical), RN7SKP37 (55% identical), RN7SKP78 (55% identical), RN7SKP124 (55% identical), and 284 more.